DNAJB1 (DnaJ heat shock protein family (Hsp40) member B1)
Diseases named in the same sentence as DNAJB1 in open-access papers (continued):
Sharing a sentence is not in itself a finding about the gene and the disease.
cholangiocarcinoma (3 papers, 2020 to 2022). A carcinoma that arises from the intrahepatic biliary tree (intrahepatic cholangiocarcinoma) or from the junction, or adjacent to the junction, of the right and left hepatic ducts (hilar cholangiocarcinoma). "Previous studies have reported that DNAJB1 expression, which is upregulated in the tissues, cell lines, and bile of cholangiocarcinoma, can serve as a new biomarker for cholangiocarcinoma." (PMID 32984053, 2020). "Additionally, DNAJB1/HDJ1 is identified as a biomarker for cholangiocarcinoma." (PMID 34948322, 2021).
Huntington disease (3 papers, 2022). Huntington disease (HD) is a rare neurodegenerative disorder of the central nervous system characterized by unwanted choreatic movements, behavioral and psychiatric disturbances and dementia. "Activation of SNCA in Huntington’s disease conveys an inhibitory effect on DnaJ heat shock protein family (Hsp40) member B1 (DNAJB1)." (PMID 36523604, 2022).
Spinocerebellar ataxia type 3 (3 papers, 2018 to 2023). "For instance, DNAJB1 is involved in the clearance of mutant polyglutamine (polyQ) protein Ataxin-3 aggregates and is suppressed in spinocerebellar Ataxia Type 3 (SCA3)." (PMID 37104008, 2023). "An investigation on a model for Spinocerebellar Ataxia Type 3 (SCA3) revealed a functional role for DNAJB1 in the clearance of mutant polyglutamine (polyQ) protein ataxin-3 aggregates." (PMID 34234816, 2021). "In spinocerebellar ataxia type 3 (SCA3), the co-chaperone DnaJ homology subfamily B member 1 (DNAJB1 or heat shock protein 40) is recruited to protein aggregates formed by the disease-causing mutant polyglutamine (polyQ) protein ataxin-3 (ATXN3)." (PMID 30086154, 2018).
Autoimmunity (2 papers, 2020 to 2022). The occurrence of an immune reaction against the organism's own cells or tissues. "The next three upregulated genes in treated individuals were DNAJB1, which is a part of the HSP40 complex that has been shown to play a role in anti-inflammatory processes in autoimmunity; and RGS1 and SOD1, which are important for antiviral immune responses." (PMID 36175869, 2022).
colon cancer (2 papers, 2022). "It is worth noting that previous ChIP-Seq studies on colon cancer cells found β-catenin-TCF4 on the genomic regions of HDAC1 and DNAJB1." (PMID 36551548, 2022).
esophageal carcinoma (2 papers, 2023 to 2026). A primary or metastatic malignant neoplasm involving the esophagus. "Building upon our previous research, which included exploratory analysis utilizing single-cell data from esophageal carcinoma, we elucidated the regulatory influence of DNAJB1 on naive T cells, indicating a positive correlation." (PMID 41186645, 2026).
ovarian carcinoma (2 papers, 2025). A malignant neoplasm originating from the surface ovarian epithelium. "We also observed downregulation of key HSPs including Hspa1a, Hspa1b, and Dnajb1 upon Ier5 knockdown in HM-1 and MOV ovarian cancer cells." (PMID 40002205, 2025).
tauopathy (2 papers, 2019 to 2021). Neurodegenerative disorders involving deposition of abnormal tau protein isoforms (tau proteins) in neurons and glial cells in the brain. "In a Drosophila tauopathy model, DnaJb1 knockdown stabilized cellular Tau levels." (PMID 31263146, 2019). "In contrast, DNAJB1, while showing no binding to wild-type tau, did cause noticeable reductions in peak intensities in both PHF6 motifs of the P301S and P301L tauopathy mutants." (PMID 34369377, 2021).
thyroid cancer (2 papers, 2018 to 2022). "In conclusion, we developed a novel seven-mRNA (CDKN2A, FGF7, CTSB, HAP1, DAPK2, DNAJB1, ITPR1) risk model and nomogram that could help assess the prognosis of patients and guide clinical decision-making and individualized therapy for differentiated thyroid cancer." (PMID 35459137, 2022).
B-cell lymphoma (1 paper, 2022). "Here we have assessed the expression of various HSP families, including cytosolic (HSP90α, HSP90β, HSP70, HSC70, and HSP40/DNAJB1), endoplasmic reticulum (GRP78), and mitochondrial (HSP60) HSP homologs in resting and CD3/CD28-stimulated T cells in healthy controls and B-cell lymphoma patients." (PMID 36359267, 2022).
biliary atresia (1 paper, 2024). A rare, biliary tract disease characterized by progressive obliterative cholangiopathy of the intra- and extrahepatic bile ducts, occurring in the embryonic/ perinatal period, leading to severe and persistent neonatal jaundice and acholic stool. "Expression of DNAJB1-PKAc in patients with biliary atresia correlates with an increased expression of oncogenes." (PMID 39796711, 2024).
cataract (1 paper, 2016). Partial or complete opacity of the crystalline lens of one or both eyes that decreases visual acuity and eventually results in blindness. "Nevertheless, it is unlikely that the chaperone activity of DNAJB1 is the cause of these cataracts, as CRYAA, CRYAB and HSP90 are expressed at high levels in the lens and should be able to compensate for the loss of chaperone action." (PMID 27218149, 2016).
chronic myelogenous leukemia (1 paper, 2019). "These include BCR–ABL1, found in ~ 95% of chronic myelogenous leukemia (CML) patients; TMPRSS2–ERG in ~ 50% of prostate cancers; and DNAJB1–PRKACA, the hallmark and likely driver of fibrolamellar carcinoma." (PMID 31639029, 2019).
emphysema (1 paper, 2023). "In the lung tissues of CS‐induced emphysema mice models, miR‐23a‐3p was lowly expressed, whereas DNAJB1 was highly expressed." (PMID 37828807, 2023). "Here, we discovered that miR‐23a‐3p and DNAJB1 were differentially expressed in CS‐induced emphysema mice models and CSE‐induced PMVECs, and bioinformatics analysis indicated that there were potential binding sites between them." (PMID 37828807, 2023). "WB analysis confirmed the high expression of DNAJB1, and IHC staining further detected the increased DNAJB1 expression in the lung tissues of CS‐induced emphysema mice models." (PMID 37828807, 2023). "In the lung tissues of CS‐induced emphysema mice models, miR‐23a‐3p mimics significantly elevated miR‐23a‐3p expression and reduced DNAJB1 mRNA and protein expression." (PMID 37828807, 2023). "MiR‐23a‐3p was downregulated, and DNAJB1 was upregulated in CS‐induced emphysema mice models and CSE‐induced PMVECs." (PMID 37828807, 2023). "Additionally, miR‐23a‐3p alleviated lung tissue injury and improved emphysema in mice by reducing DNAJB1 expression." (PMID 37828807, 2023). "Our findings revealed that targeted miR‐23a‐3p/DNAJB1 axis might be used for emphysema treatment, which provided a novel therapeutic strategy for emphysema." (PMID 37828807, 2023). "Therefore, we proposed the hypothesis that miR‐23a‐3p regulated emphysema progression through DNAJB1, hoping to provide potential molecular targets for emphysema treatment." (PMID 37828807, 2023). "The present study revealed that miR‐23a‐3p repressed cigarette smoke‐induced emphysema in mice and CSE‐induced PMVECs apoptosis by targeting DNAJB1." (PMID 37828807, 2023). "Therefore, our study explored the functions of miR‐23a‐3p and DNAJB1 in CS‐induced emphysema in mice and CSE‐induced PMVECs apoptosis, with a view to providing potential molecular targets for emphysema treatment." (PMID 37828807, 2023). "MiR‐23a‐3p alleviated emphysema progression, which could inhibit CSE‐induced PMVECs apoptosis by targeting DNAJB1." (PMID 37828807, 2023). "However, the specific role of DNAJB1 in emphysema is not yet known." (PMID 37828807, 2023).
esophageal squamous cell carcinoma (1 paper, 2017). Esophageal squamous cell carcinoma (ESCC) is a type of esophageal carcinoma (EC) that can affect any part of the esophagus, but is usually located in the upper or middle third. "DNAJB1 is a well-studied oncogene that could promote cell proliferation and has also been reported as an SE-associated oncogene in esophageal squamous cell carcinoma." (PMID 29285248, 2017).
experimental autoimmune encephalomyelitis (1 paper, 2022). An autoimmune demyelinating disease of the central nervous system that is produced experimentally in animals by the injection of homogenized brain or spinal cord in Freund's adjuvant. "Moreover, they showed that the miR-155 targeted the heat shock proteins family-40 containing Dnajb1 and Dnajb2, which could regulate Th17 cell differentiation and decrease experimental autoimmune encephalomyelitis and demyelination." (PMID 35676653, 2022).
HCMV infection (1 paper, 2024). "In particular, the HSPs DNAJB1 and HSPA1A were the host genes that were most positively correlated with viral RNA expression in P. Thus, here we identified putative pro- and anti-viral host factors of HCMV infection in moDCs." (PMID 38409141, 2024).
jejunal cancer (1 paper, 2022). A malignant neoplasm involving the jejunum. "We found that some upregulated DEGs in GC malignant cells such as HSPB1, PHLDA2, DNAJB1 have the decreasing expression tendency in malignant cells from GC, duodenal caners, jejunal cancers to CRC." (PMID 36104333, 2022).
major depressive disorder (1 paper, 2026). An episode of depression lasting two or more weeks without an intervening episode of mania. "The analysis of mRNA expression in the prefrontal cortex of suicide victims with major depressive disorder revealed a differential profile with 27 downregulated mRNAs, including HSPA1A, HSPA1B, DNAJB1, NR4A1, and GADD45B, which are involved in proteostasis, transcriptional regulation, and apoptosis." (PMID 41977312, 2026).
multiple sclerosis (1 paper, 2022). A progressive autoimmune disorder affecting the central nervous system resulting in demyelination. "The maximum reduction of Dnajb1/Dnajb2/Foxp1/Tnfsf14 network was observed when Multiple sclerosis rats were treated with exercise training and 100 mg/kg Royal jelly (ET-RJ100), but the relative expression of the Hspa4 significantly increased." (PMID 35676653, 2022). "The maximum reduction of the Dnajb1/Dnajb2/Foxp1/Tnfsf14 network was observed when Multiple sclerosis rats were treated with exercise training and 100 mg/kg Royal jelly (ET-RJ100), but the relative expression of the Hspa4 significantly increased." (PMID 35676653, 2022). "This study presented a list of bioactive compounds with suitable binding affinity over the DNAJB1 and TNFSF14 as the cutpoint proteins in the multiple sclerosis network based on a molecular docking survey." (PMID 35676653, 2022).
pancreatic ductal adenocarcinoma (1 paper, 2020). An infiltrating adenocarcinoma that arises from the epithelial cells of the pancreas. "In addition, several researches have demonstrated that the DNAJB1–PRKACA gene fusion can also be found in the pancreatic and biliary intraductal oncocytic papillary neoplasm (IOPN), as well as in the intraductal papillary mucinous neoplasm (IPMN) of pancreas and pancreatic ductal adenocarcinoma." (PMID 32984053, 2020).
schizophrenia (1 paper, 2016). A major psychotic disorder characterized by abnormalities in the perception or expression of reality. "The schizophrenia specific module, SCH_only_M7, was not correlated with any covariates we tested and contained 76 genes with BAG3, DNAJB1,DNAJB4, HSPAH and HSPA6 the top 5 hub genes in this module." (PMID 27898074, 2016).
vascular dementia (1 paper, 2025). A degenerative vascular disorder affecting the brain. "Based on these results, HSP90AA1, HSPA1B, and DNAJB1 show considerable potential as diagnostic and therapeutic targets for vascular dementia, offering crucial molecular-level support for clinical diagnosis and subsequent treatment strategy formulation in VaD." (PMID 40808948, 2025). "This study, through the integration of multi-omics data and cross-validation with machine learning algorithms, systematically elucidates the pivotal regulatory roles and diagnostic value of heat shock protein family members HSP90AA1, HSPA1B, and DNAJB1 in vascular dementia (VaD)." (PMID 40808948, 2025). "This study integrates multi-omics data and machine learning to elucidate the immune-neurovascular regulatory roles of HSP90AA1, HSPA1B, and DNAJB1 in vascular dementia (VaD), supporting the core hypothesis that protein homeostasis imbalance drives VaD-related neuroinflammation." (PMID 40808948, 2025).
ZIKV infection (1 paper, 2019). "Hsp70 is also in association with DNAJB1, which is known to mediate cellular RNA sensing by interacting with MDA5/MAVS that could be validated for ZIKV infection in future studies." (PMID 30866755, 2019).
cancer (90 papers, 2014 to 2026). A tumor composed of atypical neoplastic, often pleomorphic cells that invade other tissues. "Moreover, a pan-cancer study identified a tumor-enriched NK cell subset—tumor-associated NK (TaNK) cells—which display elevated stress-response genes (e.g., DNAJB1/HSP40) and reduced levels of cytotoxic molecules (e.g., granzyme B, perforin)." (PMID 40297580, 2025). "DNAJB1/HDJ1 is also implicated in cancer progression and therapeutic resistance." (PMID 34948322, 2021). "In clinical cancer, PRKACA participates in a fusion event with DNAJB1 in up to a hundred percent of fibrolamellar hepatocellular carcinoma and has therefore been identified as a suitable diagnostic marker for and a driver of oncogenic activities in that cancer." (PMID 39458904, 2024). "The phase I clinical trial FusionVAC22_01 will enroll patients with FL-HCC or other cancer entities carrying the DNAJB1-PRKACA fusion transcript that are locally advanced or metastatic." (PMID 38606105, 2024). "DNAJB1 has four phosphorylation sites in its cytosolic domain that alter its nuclear transport and directly affect DNAJB1’s role in cancer progression." (PMID 39433125, 2024). "Accumulating reports have indicated that DNAJB1 is an unfavorable prognostic marker in cancer progression and therapeutic resistance." (PMID 36499297, 2022). "The recent discovery of the DNAJB1-PRKACA fusion transcript in FL-HCC has been a major advancement in our understanding of the pathogenesis of this deadly cancer." (PMID 31489118, 2019). "In 38 tumor-specific SE-associated genes, 37 genes showed significantly elevated expression in at least 1 cancer cell line, including DNAJB1, MCU, MPRIP and PSAP." (PMID 29285248, 2017). "In a variety of cancers, these 4 up-regulated genes (DNAJB1, MCU, MPRIP and PSAP) have been reported to be related to drug-resistance processes, cell death, cancer invasion and metastasis." (PMID 29285248, 2017). "Although the role of Hsp70 in cancer development is well documented, data concerning the function of its most abundant cellular co-chaperones, Hdj1 (DNAJB1) and Hdj2 (DNAJA1), in the process remain elusive." (PMID 26959111, 2016). "By Min Qi and colleagues, they found that HSP40/DNAJB1 inhibited cancer cell growth in vitro and in vivo by stabilizes MDM2, which was consistent to our results although it worked though two different pathways." (PMID 24658033, 2014). "Notably, D_FB1 displays elevated levels of other cancer‐ and inflammation‐related genes—such as DNAJB1, ZFP36, JUND, TNFAIP3 and IL6—further underscoring a microenvironment characterised by heightened cellular stress and chronic inflammation." (PMID 41055332, 2026). "While we presume that the same cancer recurred, we cannot exclude the possibility that this patient harbored a liver field defect (for example, the presence of a DNAJB1-PRKACA fusion in the background liver) that resulted in the development of two independent FLC tumors." (PMID 39119399, 2024). "Studies suggest that export of DnaJB11 enhances extracellular proteostasis, that intercellular movement of DnaJB1 or DnaJB6 enhances the proteostasis capacity in recipient cells, whereas the import of DnaJB8 increases resistance to chemotherapy in recipient cancer cells." (PMID 36581212, 2023). "Importantly, some DNAJB proteins, including DNAJB1/HDJ1, DNAJB4/HLJ1, DNAJB6/MRJ, DNAJB8, DNAJB9/MDG1/ERdj4, DNAJB11/ERdj3/HEDJ, and DNAJB12, are implicated in cancer progression." (PMID 34948322, 2021). "However, significant enhancement of ALDOA, TPI1, and DNAJB1 in MD/PD/WD metastatic OSCC compared to WD OSCC suggests enhanced cancer cell proliferation, metabolic reprogramming and oncogenic stress in the former." (PMID 32922662, 2020).